CDKN2A (cyclin dependent kinase inhibitor 2A)
Diseases named in the same sentence as CDKN2A in open-access papers (continued):
Sharing a sentence is not in itself a finding about the gene and the disease.
astrocytomas (continued). "CDKN2A/B HD was adopted as a criterion for grade 4 IDH-mutant astrocytomas in the WHO CNS Tumour Classification 2021 (in addition to morphologic features)." (PMID 37504251, 2023). "The new entity of grade 4 astrocytoma with CDKN2A/B HD encompasses IDH-mutant astrocytomas previously treated with different regimens." (PMID 37504251, 2023). "Taking CDKN2A/B into the evaluation scheme of IDH‐mutant astrocytoma specifies a more straightforward prognosis‐directed treatment pathway for various patients." (PMID 37667984, 2023). "Consistent with YMG25R parent tumor cells, gain of PDGFRA and amplification of CDK4 and MDM2 were observed, while CDKN2A HD was identified in the xenografts, qualifying for astrocytoma, IDH-mutant, CNS WHO grade 4 according to the WHO CNS5 criteria." (PMID 38012788, 2023). "To verify if IDH1/2-mutant astrocytomas with CDKN2A, PDGFRA, CDK4, or MDM2 CNA promotes poor prognosis, we used the GLASS and MSK diffuse glioma datasets (total 1,448 cases)." (PMID 38012788, 2023). "Interpreting the impact of CDKN2A/B alterations on astrocytoma prognosis is complicated by recent changes in tumour classification and a lack of uniform standards for testing CDKN2A/B." (PMID 37504251, 2023). "Although this analysis included both astrocytomas and oligodendrogliomas, the authors noted that of the three studies reporting 1p/19q co-deletions, when the co-deletion was excluded, CDKN2A retained its prognostic value." (PMID 37504251, 2023). "Although the overall prognostic significance is still controversial, a large-scale study demonstrated that in addition to CDKN2A/B deletion, CDK4 amplification, which also deregulates Rb pathway, was associated with poor prognosis in IDH-mutant astrocytoma." (PMID 38012788, 2023). "For instance, CDKN2A/B homozygous deletion has been included for diagnosing WHO_Grade4_IDH-mutant_astrocytomas." (PMID 36720864, 2023). "IDH-mutant astrocytomas with MMR mutations were significantly more likely to present at higher grade (P < .0001) and had more frequent homozygous CDKN2A deletion (P = .0021) than their MMR wild-type counterparts." (PMID 37554222, 2023). "The CDKN2A/B homozygous deletion is also identified independently from BRAF activation as a biomarker of high-grade astrocytomas with a worse clinical outcome." (PMID 36831610, 2023). "About 39% of IDH-mutant, grade-4 astrocytomas were grade 2/3 astrocytomas with CDKN2A/B homozygous deletion." (PMID 36998447, 2023). "Most recently, there has been considerable interest in the effect of CDKN2A and/or CDKN2B (CDKN2A/B) homozygous deletions (HD) on the prognosis of isocitrate dehydrogenase (IDH)-mutant astrocytomas." (PMID 37504251, 2023). "A significant proportion (6–20%) of grade 4 IDH-mutant astrocytomas with CDKN2A/B HD were previously classified as either grade 2 or grade 3 tumours." (PMID 37504251, 2023). "In TCGA, the majority of grade 4 IDHmut astrocytomas (68%) had a homozygous deletion of CDKN2A, which also led to reduced expression at the RNA level." (PMID 37932833, 2023). "Proposed a combined molecular model that included CDKN2A homozygous deletions to prognosticate in IDH-mutant astrocytomas." (PMID 37504251, 2023). "Both within GLASS and TCGA IDHmut astrocytomas, the inactivation of CDKN2A and RB1 was mainly mutually exclusive." (PMID 37932833, 2023). "Consistent with parent recurrent tumor cells, amplifications of CDK4 and MDM2 and PDGFRA gain were found, while CDKN2A/B was identified as homozygous deletion in the xenografts, qualifying for integrated diagnosis of astrocytoma, IDH2-mutant, CNS WHO grade 4." (PMID 38012788, 2023). "WHO grade 4 tumors with IDH1-mut should mostly belong to astrocytoma, IDH1-mut and WHO grade 4 (exclude CDKN2A/B mutation)." (PMID 37029174, 2023).
astrocytomas (continued). "The first study to propose a grade 4 diagnosis for IDH-mutant astrocytoma in the presence of CDKN2A/B." (PMID 37504251, 2023). "The remaining astrocytomas and oligodendrogliomas with retained CDKN2A/B kept their histological grade." (PMID 36739454, 2023). "To this end, we reviewed the literature on different CDKN2A/B alterations in IDH-mutant astrocytomas and their impact on diagnosis and management." (PMID 37504251, 2023). "To guide understanding and management of this newly defined group, we performed a literature review on CDKN2A/B HD in astrocytomas." (PMID 37504251, 2023). "Amplification of platelet-derived growth factor receptor (PDGFR) genes, CDKN2A/2B homozygous deletion, and PI3K (phosphoinositide 3-kinase) mutations have been recently associated with worse prognosis in grade 3 astrocytomas." (PMID 36831383, 2023). "CDKN2A/B homozygous deletion has recently been included as a grading biomarker for IDH-mutant astrocytomas in the 2021 WHO classification criteria of CNS tumors." (PMID 36739454, 2023). "The presence of CDKN2A/B homozygous deletion differed in one out of two patients with IDH-mutant astrocytomas, CNS WHO grade 4." (PMID 35701666, 2022). "Multiple studies have identified the homozygous deletion of CDKN2A/B as a marker of poor prognosis in patients with IDH-mutant astrocytomas, and a correlation with shorter survival has been confirmed in several studies." (PMID 35693015, 2022). "IDH-mutant astrocytomas are considered a distinct entity and categorized as Grade 2, 3, or 4, while CDKN2A/B deletions provide further subclassification to IDH-mutant astrocytomas." (PMID 36147920, 2022). "The average copy number for CDKN2A was 1.09 ± 0.75 in IDH-wildtype infiltrating astrocytoma, 1.73 ± 0.68 in IDH-mutant infiltrating astrocytoma, and 1.94 ± 0.41 in oligodendroglioma." (PMID 36397144, 2022). "Of these, the vast majority were IDH-wildtype infiltrating astrocytoma (67/77; 87.0%) with IDH mutant infiltrating astrocytoma being the second most common tumor type for which CDKN2A loss was detected by targeted NGS (5/77; 6.5%)." (PMID 36397144, 2022). "The 2021 WHO classification considers the homozygous deletion of CDKN2A/B as a molecular feature of grade 4 in IDH-mutant astrocytomas and also as a molecular feature of grade 3 oligodendroglioma." (PMID 35693015, 2022). "In particular, amplification of PDGFR (platelet-derived growth factor receptor) genes, CDKN2A/CDKN2B homozygous deletion, and PI3K mutations were independently associated with worse prognosis in patients with anaplastic (WHO grade 3) astrocytomas." (PMID 35875065, 2022). "After stratifying the cases according to the IDH1 gene, we noticed that the impact of altering the CDKN2A gene, associated with mortality, was higher in the case of IDH-mutant astrocytomas (p = 0.002)." (PMID 36136867, 2022). "We identified intratumor heterogeneity of the CDKN2A/B deletion in one of the two IDH-mutant astrocytomas, CNS WHO grade 4 in our cohort after excluding samples with low tumor purity." (PMID 35701666, 2022). "In PMMRDIA, the RB1 gene was affected by point mutations more frequently (23.5% vs. 4.6%) whereas deletions of CDKN2A/B were present less frequently (35% vs. 70%) compared to the reference cohort of high-grade supratentorial IDH-mutant astrocytomas." (PMID 33216206, 2021). "On the other hand, CDKN2A mutation indicates the highest malignancy grade in the group of diffuse, IDH-mutant astrocytomas." (PMID 34638714, 2021). "Histological findings of necrosis or vascular proliferation (or both) or homozygous CDKN2A/B deletion allow for the diagnosis of an astrocytoma, IDH-mutant, WHO grade 4." (PMID 33216206, 2021).
astrocytomas (continued). "We performed two sensitivity analyses including only IDH-mut astrocytomas verified to lack CDKN2A/B homozygous deletion (n=55)." (PMID 35083156, 2021). "It is also worth noting that the original tumor had homozygous loss of CDKN2A, which has prognostic relevance in patients with histologically confirmed GBM in addition to lower-grade astrocytomas." (PMID 34193272, 2021). "Multivariate Cox-PH analysis revealed that the prognostic significance of CDKN2A in IDHm astrocytomas is optimized by using a cutoff value of ≥ 30% of tumor cells with homozygous deletion in order to define tumor-wide “homozygous deletion” status." (PMID 33081848, 2020). "Our findings differ from those studies showing a significant prognostic impact of CDKN2A deletion in both grade 3 and grade 4 IDHm astrocytomas, as detected by array-based techniques." (PMID 33081848, 2020). "In conclusion, CDKN2A homozygous deletion is a marker of poor prognosis in histologic grade 4 IDHm astrocytomas, but the impact of this finding in histologic grades 2 and 3 tumors is less clear." (PMID 33081848, 2020). "This comparison with the published literature further supports our findings that grade 2/3 astrocytomas with CDKN2A homozygous deletion as assessed by FISH have longer survival than histologic grade 4 tumors." (PMID 33081848, 2020). "For astrocytoma, BRAF, ATM, CDKN2A, and EGFR mutations/amplifications were highly enriched in our cohort." (PMID 32373528, 2020). "The ability to accurately and reliably detect CDKN2A homozygous deletion in IDHm astrocytomas is necessary if this is to be included as a grade defining criteria in the next revision of the WHO Classification." (PMID 33081848, 2020). "Our findings are consistent with literature, since we report CDKN2A deletions in 28 from 63 cases (44.4%), with significantly higher frequency of both heterozygous and homozygous deletion in astrocytomas (p ≤ 0.0001 and p = 0.006 respectively)." (PMID 31151164, 2019). "Astrocytomas demonstrated a significantly higher frequency of both CDKN2A heterozygous (16/47 cases, 34%) and homozygous deletion (8/47 cases, 17%) than other histological groups (p ≤ 0.0001 and p = 0.006, respectively)." (PMID 31151164, 2019). "There is also evidence suggesting homozygous deletion of CDKN2A/B identifies poor prognosis IDHmt astrocytoma." (PMID 30470264, 2018). "IDH wild-type GBM-Os in our cohort, on the other hand, were characterized by chromosome 7 gains, chromosome 10 losses, and 9p (CDKN2A) deletions; signatures of an astrocytoma lineage and most typical of IDHwt GBM." (PMID 26757882, 2016). "The results in the literature differ in relation to the pattern of methylation of the CDKN2A promoter region in astrocytomas." (PMID 26317630, 2015). "Because these inhibitors yield encouraging clinical results in other cancers, our findings indicate a rational therapeutic strategy for treating a subset of pediatric astrocytomas with BRAFV600E mutation and CDKN2A deficiency." (PMID 25008045, 2014). "In pediatric gliomas, we recently described the generation of a high-grade astrocytoma model that recapitulates the genetics of a subset of tumors with mutated BRAFV600E and CDKN2A deletion." (PMID 25008045, 2014). "A subset of high-grade pediatric astrocytomas into which our patient fits has a BRAF mutation and CDKN2A inactivation." (PMID 25563358, 2014).
astrocytomas (continued). "Molecular anomalies typical for astrocytomas (TP 53 mutations, EGFR gene overdosage, CDKN2A deletion; LOH 10p, LOH 10q) identified in original tumours used for the generation of cell cultures were applied as potential markers of tumour cells." (PMID 25788865, 2014). "CDKN2A/B deletion was also observed in Res259 astrocytoma cells, which also contained the well-described 4q12 amplicon, resulting in high level gains of the oncogenes PDGFRA and KIT, and low-level gain of a region including KDR/VEGFR2." (PMID 19365568, 2009). "The molecular profile-especially the presence of any CDKN2A/B deletion-may define a more aggressive subtype of IDH-mutant astrocytoma." (PMID 42294286, 2026). "Additionally, intrachromosomal events such as codeletion of CDKN2A/B in astrocytoma are reliably detected." (PMID 40392954, 2025). "Amongst IDH1/2-mutant astrocytoma in the non-TCGA cohort, CDKN2A/B loss (hemizygous or homozygous) was the strongest negative prognostic feature (HR: 2.81, 95%CI: 1.8–4.4) after adjusting for demographic, molecular, and treatment variables." (PMID 39584448, 2025). "In addition, homozygous deletion of the CDKN2A/B locus has recently been implemented as a molecular marker for grade 4 IDH-mutant astrocytomas." (PMID 39899075, 2025). "Homozygous deletion of CDKN2A/B is uniformly associated with a worse prognosis in GBM and IDH-mutant astrocytoma, which may partially explain the aggressive behavior of HGAP." (PMID 40270074, 2025). "Further research based on the findings is necessary to validate the efficacy of H3K27me3/EZH2 for predicting the malignancy of astrocytoma, IDH-mutant and to explore the association of H3K27me3/EZH2 with the molecular features of CDKN2A/B HD or the radiological characteristics." (PMID 39636550, 2025). "IDHmut-astrocytomas with any CDKN2A/B loss clustered together, regardless of grade, and exhibited the poorest outcomes." (PMID 39584448, 2025). "In addition to the adverse prognostic impact of homozygous deletions of CDKN2A/B in astrocytomas as acknowledged in the current WHO 2021 classification, also an association of hemizygous deletions has been described recently." (PMID 39954095, 2025). "IDH mutant astrocytomas with CDKN2A/B homozygous deletions have significantly shorter survival." (PMID 40949165, 2025). "All cases with positive T2-FLAIR mismatch sign had CDKN2A-intact astrocytoma." (PMID 39117984, 2024). "High-grade astrocytoma with piloid features (HGAP) is a distinct tumour type but has morphological overlap with pilocytic astrocytoma and also typically carries a variant driver in the MAPK pathways (often with additional variants in ATRX and/or CDKN2A/B)." (PMID 39294363, 2024). "CDKN2A HD was detected in 20 (22.7%) of 88 astrocytoma cases." (PMID 38109891, 2024). "This imaging biomarker may enable preoperative prediction of the CDKN2A status among patients with astrocytoma, IDH-mutant." (PMID 39117984, 2024). "Eighty-eight astrocytomas and 71 oligodendrogliomas cases that were diagnosed between 2014 and 2021 at Hacettepe University were selected and tissue microarrays were conducted to perform CDKN2A fluorescence in situ hybridization and MTAP IHC." (PMID 38109891, 2024). "IDH-mutant astrocytomas with homozygous CDKN2A deletion showed lower LINE-1 methylation levels than IDH-mutant astrocytomas without complete CDKN2A loss." (PMID 38183430, 2024). "All the CDKN2A-HD astrocytomas were located in the frontal lobe (5 cases)." (PMID 39117984, 2024). "CDKN2A homozygous deletion, PDGFRA amplification, and CDK4 amplification were found to be associated with shorter progression‐free survival (PFS) and overall survival (OS) in WHO grade II–III astrocytoma with IDH‐mutant." (PMID 38970209, 2024). "Moreover, homozygous deletion of the CDKN2A/CDKN2B tumor suppressor gene locus has been introduced as a molecular biomarker for CNS WHO grade 4 in an IDH-mutant astrocytoma." (PMID 38183430, 2024).
astrocytomas (continued). "Examples include the combined loss of chromosome 1p/19q as an essential diagnostic criterion for IDH-mutant oligodendroglioma, or homozygous deletions of CDKN2A/B as a grading criterion for IDH-mutant astrocytoma (WHO Classification of Tumours Editorial Board 2021)." (PMID 38244574, 2024). "We observed that 2/60 (3%) IDHmut astrocytomas were reclassified as A4IDHmut due to CDKN2A/B homozygous deletion and 5/60 (8%) of IDHwt grades 2 and 3 were reclassified as GBMs (grade 4) due to one or more alterations in TERT, EGFR, and chromosomes 7 and 10, under the 2021 WHO criteria." (PMID 38672598, 2024). "This imaging biomarker may enable preoperative prediction of CDKN2A status among astrocytoma, IDH-mutant." (PMID 39117984, 2024). "If CDKN2A/B is homozygously deleted, the classification becomes an astrocytoma grade 4." (PMID 38203783, 2024). "IDH-mutant astrocytoma grade 4 was defined as a diffusely infiltrative astrocytic glioma with an IDH1 or IDH2 mutation that exhibited microvascular proliferation or necrosis, CDKN2A/B homozygous deletion, or any combination of these features." (PMID 39457569, 2024). "In this study, we explored the association between the T2-FLAIR mismatch sign and the CDKN2A status among non-enhancing astrocytoma, IDH-mutant with other radiological characteristics." (PMID 39117984, 2024). "Due to this, homozygous CDKN2A/B deleted IDH-mut astrocytomas are classified as WHO grade 4." (PMID 39593128, 2024). "Therefore, the strongest evidence for CDKN2A/B HD in IDH-mutant astrocytomas must come from prospective reports with the current WHO 2021 classification." (PMID 37504251, 2023). "In diffuse IDH-MT astrocytoma, CDKN2A is a marker of the highest malignancy grade." (PMID 37908227, 2023). "Further reports using methylation data and FISH later emerged, indicating CDKN2A could stratify IDH-mutant astrocytomas, either alone or in combination with other molecular alterations." (PMID 37504251, 2023). "Interestingly, two CNS WHO grade 4 astrocytomas harboring CDKN2A/B homozygous deletions were classified with the lower-grade astrocytoma subclass by methylation profiling, although one of the samples received a low classification score (< 0.90)." (PMID 36739454, 2023). "There is also a paucity of data on the management of CDKN2A/B HD IDH-mutant astrocytomas." (PMID 37504251, 2023). "They analysed 56 astrocytoma specimens (based on morphologic criteria, IDH status unknown) and found 17 specimens had p16 alterations (CDKN2A HD = 7, CDKN2A mutation = 5, p16 loss on IHC = 5)." (PMID 37504251, 2023). "Other studies reported a more mixed effect of CDKN2A/B on IDH-mutant astrocytoma prognosis." (PMID 37504251, 2023). "Unfortunately, the evidence for treatment specifically for CDKN2A/B HD astrocytomas is minimal." (PMID 37504251, 2023). "Fifty-eight grade 2–3 IDH-mutant astrocytomas were identified, 50 with CDKN2A/B results." (PMID 37316586, 2023). "Furthermore, clinical trials that use the current WHO 2021 classification are required to determine the optimal management of IDH-mutant astrocytomas with CDKN2A/B HD." (PMID 37504251, 2023). "In IDH-mutant astrocytomas, CDKN2A/B homozygous deletion is an adverse prognostic factor." (PMID 36826144, 2023). "Notably, the comparison between astrocytoma and oligodendroglioma revealed statistically significant differences in age at surgery and CDKN2A/B status, as anticipated." (PMID 37717080, 2023). "Demonstrated CDKN2A as a strong predictor for OS in IDH-mutant astrocytomas." (PMID 37504251, 2023).